MTDH (metadherin)
Diseases named in the same sentence as MTDH in open-access papers (continued):
Sharing a sentence is not in itself a finding about the gene and the disease.
lung carcinoma (26 papers, 2011 to 2023). "They found that TBK1 knockdown decreased metadherin phosphorylation at Ser568, which suggested metadherin as a downstream effector of TBK1 in lung cancer cell’s survival." (PMID 36307391, 2022). "Chen found that Huaier inhibited lung cancer proliferation and metastasis through MTDH, JAK2/STAT3, and MAPK." (PMID 35470770, 2022). "Huaier Granule extract suppresses proliferation and metastasis in lung cancer cells by downregulating the MTDH, JAK2/STAT3, and MAPK signalling pathways." (PMID 32244796, 2020). "Activation of TBK1 at mitosis was previously reported and further shown to promote phosphorylation of Plk1 and metadherin in TBK1-sensitive lung cancer cells to maintain their survival." (PMID 25923723, 2015). "In accord with these results, lung cancer cells, A549, H460 and H1299, with enhanced expression of miR-30c, or MTDH or HMGA2 knockdown exhibited a decrease in cell invasion and migration in vitro." (PMID 25340791, 2014). "By promoting Bcl-2 expression, MTDH significantly inhibited lung cancer cell apoptosis." (PMID 26287185, 2015). "Taken together, these data suggested that MTDH and HMGA2 are direct target genes for miR-30c in lung cancer." (PMID 25340791, 2014). "SNHG1 could promote NSCLC progression of lung cancer via miR-101-3p/SOX9/Wnt/β-catenin regulatory network and miR-145-5p/ MTDH axis." (PMID 29872497, 2018). "Finally, to determine if our experimental findings could be relevant to the pathogenesis of human lung cancer, we examined the expression pattern of FHIT, miR-30c, MTDH and HMGA2 in primary tumor tissues and matched lymph node metastatic tissues." (PMID 25340791, 2014). "Next, we were interested in identifying the expression patterns of FHIT, miR-30c, MTDH and HMGA2 in lung cancer progression and examined their mRNA levels in normal, non-metastatic and metastatic lung tissues." (PMID 25340791, 2014). "Currently, there are no studies demonstrating a direct relationship between MTDH and STAT3, but a recent study showed that treating lung cancer cells with a mushroom extract decreased the expression of both MTDH and STAT3, inhibiting proliferation and metastasis." (PMID 36902125, 2023). "In addition, we observed that MTDH mRNA, but not HMGA2 mRNA, was decreased in miR-30c-transfected lung cancer cells, A549, H460 and H1299 and showed inverse correlation with miR-30c in lung primary tumors." (PMID 25340791, 2014). "Finally, we demonstrate that the expression pattern of FHIT and miR-30c is inversely correlated with that of MTDH and HMGA2 in normal tissue, non-metastatic and metastatic tumors, serving as a potential biomarker for metastasis in lung cancer." (PMID 25340791, 2014).
cervical carcinoma (24 papers, 2012 to 2024). A carcinoma arising from either the exocervical squamous epithelium or the endocervical glandular epithelium. "Strong associations were observed between MTDH expression and lymph node metastasis in ovarian and cervical cancer." (PMID 27917902, 2016). "In this regard, the overexpression of MTDH has been shown to reverse the effects of the overexpressed miR-433 in cervical cancer cell lines." (PMID 33194751, 2020). "have demonstrated that cervical cancer cell lines treated with miR-433 agomir substantially decreased mRNA levels of MTDH, thus inhibiting tumor cell proliferation and invasion and triggering apoptosis." (PMID 33194751, 2020). "Metadherin (MTDH) was definitely known as a protein associated with tumor progression and metastasis in cervical cancers." (PMID 29029545, 2017). "Our results indicated that high MTDH expression is significantly correlated with higher mortality for breast, ovarian and cervical cancer." (PMID 27917902, 2016). "AEG-1/MTDH contributes to the chemoresistance of cervical cancer cells by increasing autophagy and the activation of the ERK/NF-κB pathway." (PMID 25009642, 2014). "Recent results have also indicated that AEG-1/MTDH affects the radiosensitivity of cervical cancer cells." (PMID 25009642, 2014). "It is previously reported that TNF-α up-regulates MTDH expression at both the mRNA and protein level in the human cervical carcinoma cell line HeLa." (PMID 22768080, 2012). "In addition, the high expression of MTDH is connected to the aggressive metastasis in breast, ovarian, and cervical cancers." (PMID 33802672, 2021). "While the upregulation of miR-433 in cervical cancer inhibits cell proliferation and invasion and promotes cell death, rescue experiments have demonstrated that metadherin (MTDH), an oncogene that facilitates cancer cell migration and metastasis, is a direct target gene of miR-433." (PMID 33194751, 2020). "Metadherin (MTDH) and ubiquitin specific protease 7 (USP7) have been identified to involve in the tumorigenesis of cervical cancer (CC)." (PMID 38625581, 2024).
osteosarcoma (22 papers, 2013 to 2026). A usually aggressive malignant bone-forming mesenchymal neoplasm, predominantly affecting adolescents and young adults. "miR-136 inhibits the proliferation, invasion, and migration of osteosarcoma cells by negatively regulating MTDH." (PMID 40104500, 2025). "All these findings demonstrate that the presence of circ-03955 promotes EMT in osteosarcoma by acting as miR-3662 sponge-mediated MTDH expression." (PMID 33312941, 2020). "The expression of circ-03955, MTDH, and miR-3662 was found to be inversely correlated in osteosarcoma tissues." (PMID 33312941, 2020). "Then, we used the miRanda software to predict differentially downregulated miRNAs in osteosarcoma bone samples that can interact with MTDH, including miRNA-563 and miR-3662." (PMID 33312941, 2020). "miR-3662 mimics can also inhibit the expression of MTDH, whereas miR-3662 inhibitor can promote the expression of MTDH in osteosarcoma cells from the MG-63 and U2OS cell lines." (PMID 33312941, 2020). "Our study confirmed that circ-03955 acts as a sponge to competitively inhibit miR-3662 in osteosarcoma, and downstream target MTDH was regulated by miR-3662." (PMID 33312941, 2020). "We validated MTDH to be a direct target of miR‐22 through expression studies using qRT‐PCR and western blot experiments in osteosarcoma cells." (PMID 30932352, 2019). "AEG-1/MTDH-knockdown in MG-63 osteosarcoma cells significantly decreases ET-1 expression (at the mRNA and protein levels), cell invasion, MMP-2 expression and cell survival against cisplatin." (PMID 25009642, 2014). "In osteosarcoma, it negatively regulates MTDH, exerting tumor-suppressive effects." (PMID 40104500, 2025). "In addition, circ-03955 acts as a ceRNA for miR-3662 to regulate the progression of metadherin (MTDH)-mediated osteosarcoma." (PMID 33312941, 2020). "In addition, miRNA‐618 directly targets metadherin mRNA to suppress the malignant phenotype of osteosarcoma cells by reducing phosphatase and tensin homolog (PTEN)/protein kinase B (AKT) pathway signaling." (PMID 32960473, 2020). "circ-03955 and miR-3662 regulate the effect of MTDH on osteosarcoma through endogenous competition." (PMID 33312941, 2020). "However, the relationship between miR‐22 and MTDH‐mediated autophagy in chemotherapy resistance of osteosarcoma cells remain unknown." (PMID 30932352, 2019). "It was further demonstrated that circ-03955 and miR-3662 compete to regulate the expression of MTDH, thereby affecting the proliferation, apoptosis, and EMT of osteosarcoma." (PMID 33312941, 2020). "Circ-03955 competes with miR-3662 to regulate the expression of MTDH and then affect the progression and occurrence of EMT in osteosarcoma." (PMID 33312941, 2020). "Previous studies show that circ-03955 can inhibit the progression of osteosarcoma and the occurrence of EMT and regulate MTDH expression via miRNA-3662." (PMID 33312941, 2020).
liver cancer (20 papers, 2012 to 2022). An epithelial or non-epithelial malignant neoplasm that arises from the liver. "For instance, it has been shown that elevated the expression of microRNA-30a-5p could reduce liver cancer cell growth and promotes cell apoptosis via inhibiting the MTDH/PTEN/AKT signaling pathway." (PMID 35127546, 2022).
non-small cell lung carcinoma (17 papers, 2010 to 2025). A group of at least three distinct histological types of lung cancer, including non-small cell squamous cell carcinoma, adenocarcinoma, and large cell carcinoma. "SNHG1 has been reported to up-regulated MTDH by sponging miR-145-5p and led to non-small cell lung cancer progression." (PMID 38635069, 2024). "AEG-1/MTDH is also crucial in the carcinogenesis of non-small cell lung cancer (NSCLC) and inhibits apoptosis by enhancing the level of the antiapoptotic protein, Bcl-2, and activating the PI3K/Akt pathway." (PMID 25009642, 2014). "In addition, lncRNA SNHG1 is the sponge for miR-145-5p to upregulate MTDH and enhance non-small cell lung cancer development." (PMID 33589577, 2021). "MTDH is an oncogene highly expressed in various cancers, such as breast invasive carcinoma (BRCA), non-small cell lung cancer (NSCLC), and HCC." (PMID 41318030, 2025). "In non-small cell lung carcinoma (NSCLC), MTDH induced EMT through activating Wnt/beta-catenin signaling." (PMID 28107197, 2017).
triple-negative breast carcinoma (17 papers, 2013 to 2025). An invasive breast carcinoma which is negative for expression of estrogen receptor (ER), progesterone receptor (PR), and human epidermal growth factor receptor 2 (HER2). "For instance, the long non-coding RNA (lncRNA) FAM83H-AS1 facilitates the progression of triple-negative breast cancer through binding miR-136-5p to increase MTDH expression." (PMID 38977630, 2024). "A specific H3K79 methyltransferase DOT1L increase the MTDH expression by increasing H3K79me3 levels on its promoter to promoting angiogenesis in triple-negative breast cancer." (PMID 38977630, 2024). "In triple-negative breast cancer, miR-26a is downregulated and can target metadherin to suppress cancer cell migration and proliferation." (PMID 36820066, 2023). "A previous study revealed that lncRNA OTUD6B-AS1 promoted autophagy in triple-negative breast cancer cells by regulation of the miR-26a/MTDH pathway." (PMID 36522638, 2022). "In conclusion, OTUD6BAS1/miR-26A-5p/MTDH promotes PTX resistance in triple-negative breast cancer by upregulation of autophagy and DDR inhibition mediated genomic instability." (PMID 35813295, 2022). "Another study discovered that LINC01638 was overexpressed in the tissues and cells of triple-negative breast cancer (TNBC) and that its depletion largely prevented TNBC cell proliferation and invasion through regulation of MTDH-Twist1 signaling pathway." (PMID 34281460, 2021). "Studies showed that LINC01638 was highly expressed in triple-negative breast cancer (TNBC) tissues and LINC01638 mediated TNBC progression by interacting with c-Myc and activating MTDH-Twist1 signaling." (PMID 34281460, 2021). "The expression of MTDH and that of VEGF are related to tumor angiogenesis and progression and are valuable prognostic factors for patients with triple-negative breast cancer." (PMID 34504842, 2021). "In addition, in triple-negative breast cancer, OTUD6B can activate autophagy and DDR inhibition through the OTUD6BAS1/miR-26a-5p/MTDH axis, thereby mediating genomic instability and promoting the development of PTX drug resistance." (PMID 38880876, 2024). "The study published by Liu P12et al. suggested that high MTDH level was significantly correlated with poor OS in triple negative breast cancer (P = 0.006), but no statistical significance was observed for DFS (P = 0.065)." (PMID 27917902, 2016).
neuroblastoma (16 papers, 2009 to 2021). Neuroblastoma (NB) is the most common solid, extracranial childhood tumor. "Enforced miR-145 inhibited neuroblastoma growth in vitro and in vivo by targeting MTDH, thus providing a potential target for the development of an microRNA-based approach for neuroblastoma therapy." (PMID 32083506, 2020). "It is suggested that miR-145 overexpression inhibits neuroblastoma growth by direct downregulating of MTDH." (PMID 32083506, 2020). "In vivo, miR-145 overexpression inhibits neuroblastoma growth and induced cell apoptosis, followed by downregulation of MTDH." (PMID 32083506, 2020). "Consistent with a previous study in which overexpression of MTDH promotes activation of the PI3K/AKT pathway in neuroblastoma, we detected an inhibition of components of PI3K/AKT signaling pathway in Hec50co cells with depleted MTDH as compared to control." (PMID 21687633, 2011).
glioblastoma (15 papers, 2010 to 2025). The most malignant astrocytic tumor (WHO grade IV). "This is consistent with literature data showing that FOXM1 is tightly regulated by its molecular partners that can increase FOXM1 transcriptional activity by promoting its stabilization and nuclear localization, as for instance it has been shown for the interaction with MTDH in glioblastoma." (PMID 31311575, 2019). "Furthermore, ectopic expression of a dominant-negative form of CPEB1 that does not induce polyadenylation limits the production of metadherin (MRDH), a metastasis-promoting factor, and reduces migration and tumor formation of glioblastoma cells." (PMID 36131924, 2022).
esophageal cancer (14 papers, 2010 to 2025). A primary or metastatic malignant neoplasm involving the esophagus. "MTDH is also known as AEG-1 (Astrocyte Elevated Gene 1); elevated levels have been reported in many cancers, including breast, prostate, liver, and esophageal cancers, whereas its expression is low or absent in non-malignant tissues." (PMID 40072068, 2025).
malignant glioma (14 papers, 2010 to 2023). A grade III or grade IV glioma arising from the central nervous system. "In addition, we examined the mechanism that AEG-1/MTDH enhances human malignant glioma susceptibility to TGF-β1-triggered epithelial-mesenchymal transition via autophagy induction." (PMID 27251589, 2016). "A recent study reported that in TGF-β treated malignant glioma, MTDH protein was increased via Smad2/3 phosphorylation." (PMID 30065618, 2018). "To confirm the contribution of AEG-1 in the TGF-β1-induced autophagy and EMT, we further study the effect of siRNA AEG-1/MTDH on malignant glioma cells." (PMID 26909607, 2016). "The expression of the epithelial marker E-cadherin is strongly reduced when malignant glioma cells are transfected with pcDNA3.1-AEG-1/MTDH." (PMID 26909607, 2016). "In this study we show that AEG-1/MTDH enhances protective autophagy of malignant glioma cells and promotes TGF-β1-activated EMT." (PMID 26909607, 2016). "In the present study, we focused on the regulatory mechanism of AEG-1/MTDH-mediated autophagy during malignant glioma EMT and invasion." (PMID 27251589, 2016). "In malignant glioma cells, overexpressed MTDH is located predominantly in the nucleus, where it interacts with the p65 subunit of NF-κB and CBP, thus activating NF-κB signaling." (PMID 20565850, 2010). "We further study the effect of AEG-1/MTDH overexpression on malignant glioma cells by transiently transfecting U251 and U87 malignant glioma cells with AEG-1/MTDH expression plasmid (pcDNA3.1-AEG-1/MTDH)." (PMID 26909607, 2016). "In HeLa cells and human malignant glioma cells treated with tumor necrosis factor-α (TNF-α, which induces MTDH overexpression), MTDH translocates into the nucleus where it interacts with the p65 subunit of NF-κB and upregulates NF-κB-induced gene expression." (PMID 22768080, 2012).
melanoma (14 papers, 2014 to 2021). A malignant, usually aggressive tumor composed of atypical, neoplastic melanocytes. "miR-675 targets the transcript of metadherin (MTDH) in melanoma, and the level of MTDH, which is involved in increased invasiveness of tumour cells, is inversely correlated with miR-675 expression." (PMID 30866509, 2019). "Mechanistically, miR-let-7b and miR-let-7c directly targeted metadherin (MTDH) and calumenin (CALU) and suppressed phospho-ERK in mucosal melanoma cells." (PMID 31118065, 2019).
lymph node metastasis (12 papers, 2012 to 2021). "In conclusion, our meta-analysis suggests that high MTDH expression increases risk of distant metastasis and lymph node metastasis in reproduction malignancies." (PMID 27917902, 2016). "Moreover, high MTDH expression remarkably increased the risk of distant metastasis (HR = 3.739) and lymph node metastasis (HR = 2.696) in reproduction malignancies." (PMID 27917902, 2016). "In NSCLC, AEG-1/MTDH overexpression has been found to significantly correlate with clinical staging, differentiation, lymph node metastasis and a shorter OS time." (PMID 25009642, 2014). "In gallbladder adenocarcinoma, the positive expression of EphA7 and AEG-1/MTDH has been found to significantly correlate with differentiation, tumor masses, lymph node metastasis, invasion and OS, and is an independent poor prognostic predictor, as determined by multivariate analysis." (PMID 25009642, 2014).
migraine (12 papers, 2011 to 2025). "For instance, variants in the MTDH/AEG-1 gene (known for migraine links) disrupt glutamate clearance, causing harmful buildup that affects both mood and seizure control." (PMID 40941042, 2025). "The only GWAS specifically investigating migraine with aura yielded only one single associated single nucleotide polymorphism (SNP), near MTDH and PGCP, with genome-wide significance." (PMID 32503413, 2020). "In support of a role for glutamatergic dysregulation in migraine, MTDH, a regulator of glutamate transporters, associates with the frequent form of migraine with aura." (PMID 27313535, 2016). "None of the candidates was associated with migraine; however, in gene-based analyses there was modest support for an association of MTDH, implicated in the previous GWAS, with migraine." (PMID 22072275, 2012). "Furthermore, a meta-analysis of GWAS studies in migraine patients revealed a modest gene-based association between the MTDH gene and migraine." (PMID 34148407, 2021). "Thus, the MTDH variant can indirectly affect the transport of glutamate at the synapse, supporting a role for disturbed glutamate homeostasis in migraine." (PMID 24674449, 2014). "In addition, MTDH was also recently found to be associated with migraine in a genome-wide meta-analysis including six population-based European cohorts." (PMID 24674449, 2014). "Our data indicates that rs1835740 and MTDH might be involved in neurovascular headaches in general whilst rs2651899 is specifically related to migraine." (PMID 30382894, 2018). "We have previously replicated the finding of an association for two of the established risk alleles for migraine in a Swedish migraine case-control population, rs2651899 in PRDM16 (PR/SET domain 16) and rs1835740 located between MTDH (metadherin) and PGCP (carboxypeptidase Q) on chromosome 8q22.1." (PMID 30382894, 2018). "Several genes (MTDH, LRP1, MEF2D) identified by GWAS hits for common migraine could also be linked to glutamate signalling, although these genes are not part of modules A or C." (PMID 26899160, 2016).